CTLA4 (cytotoxic T-lymphocyte associated protein 4)
Diseases named in the same sentence as CTLA4 in open-access papers (continued):
Sharing a sentence is not in itself a finding about the gene and the disease.
pancreatic cancer (continued). "Agonist anti-CD40 therapy with chemotherapy reversed the complete resistance of murine pancreatic tumors to PD-1 and CTLA-4 blockade." (PMID 32987956, 2020). "This renders pancreatic tumors responsive to the combination of dual immune checkpoint therapy and chemotherapy (anti-PD-1, anti-CTLA-4, and Gemcitabine)." (PMID 31959281, 2020). "The phase 2 trial of the anti-CTLA4 antibody, Ipilimumab, showed delayed progression in some advanced stage pancreatic cancer patients." (PMID 33226370, 2020). "A FAK inhibitor, VS-4718, was previously found to sensitize pancreatic tumors to immune checkpoint therapy, specifically anti-PD-1 and anti-CTLA-4, when used in combination with the chemotherapy Gemcitabine." (PMID 31959281, 2020). "A recent study showed that treatment with neutralizing antibodies against PD1 and CTLA4 in combination with a FAK inhibitor significantly reduced pancreatic tumor size and increased survival rates in pancreatic cancer mouse models." (PMID 32514188, 2020). "The use of single agent anti-CTLA-4 antibodies in the management of advanced PDAC has shown limited clinical benefit in the majority of pancreatic cancer patients." (PMID 31035449, 2019). "Preclinical or prospective clinical studies investigating combination regimens involving PD-1, PD-L1, or CTLA-4 inhibitors and ≥ 1 systemic therapies in the treatment of pancreatic cancer were included." (PMID 30294755, 2018). "Evidence is emerging to support combination systemic therapies on a backbone of immune checkpoint inhibition to overcome resistance to single-agent PD-1/PD-L1/CTLA-4 blockade in pancreatic cancer." (PMID 30294755, 2018). "Pancreatic cancer has been refractory to immunotherapy through CTLA-4, PD-1 or PD-L1 antibodies that have been promising for many advanced solid tumors." (PMID 28122342, 2017). "An ongoing study (NCT02301130) currently investigates the combination of mogamulizumab (an anti-CCR4 mAb) with either MEDI4736 (anti-B7H1 mAb) or tremelimumab (anti-CTLA-4 mAb) to overcome the immunosuppression in pancreatic cancer." (PMID 27141395, 2016). "These patients also respond poorly to immune checkpoint blockade therapies (anti-CTLA-4, anti-PD-L1, anti-PD-1), which suggests the presence of additional immunosuppressive mechanisms in the pancreatic tumour microenvironment (TME)." (PMID 26918344, 2016). "A cell-based cancer vaccine, GVAX, was able to induce the formation of tertiary lymphoid aggregates in pancreatic cancer patient tumours, and resulted in objective clinical responses in combination with anti-CTLA-4." (PMID 26918344, 2016). "However, in pancreatic cancer, IL‐17 inhibition increases sensitivity to PD‐1 and CTLA4 offering potential improvements in cancer treatment strategies." (PMID 41503514, 2026). "A reasonable explanation might be the higher CTLA-4 mRNA expression in T-regulatory cells of pancreatic cancer patients and higher CTLA-4 expression at the time of disease progression." (PMID 37185406, 2023). "A study in pancreatic cancer demonstrated that CSF-1/CSF-1R blockade up-regulated PD-L1 and CTLA-4, justifying that the combination of TAM reprogramming therapy with ICB may yield maximum effect." (PMID 37251409, 2023). "Combined IL-6 and CTLA-4 blockade increases T cells in pancreatic tumors." (PMID 36881480, 2023). "However, pancreatic cancer, as an extremely malignant tumor with a poor prognosis, has low immunogenicity, and common immune checkpoint blockers such as CTLA-4 or PD-1 inhibitors are ineffective for pancreatic cancer patients." (PMID 36505775, 2022). "Anti-hMARCO treatment could thus be used as a combinatory immunotherapy with anti-CTLA-4/anti-PD-1/PD-L1 to improve the efficacy of checkpoint therapies in pancreatic cancer patients." (PMID 36310582, 2022). "Similarly, combining GM-CSF with CTLA-4 blocking mAb ipilimumab improved tumor antigen-specific T cell responses in prostate and pancreatic cancer in comparison to either GM-CSF or ipilimumab alone." (PMID 35865534, 2022).
pancreatic cancer (continued). "CTLA4 upregulation has also been evidenced in neoplastic diseases such as pancreatic cancer." (PMID 34735462, 2021). "The latest data suggest that inhibiting the interaction between CXCR4 expressing T cells and CXCL12 secreting cells in the microenvironment may modulate anti-CTLA-4 or anti-PD-1 immunotherapy in pancreatic cancer and HCC." (PMID 33790943, 2021). "In general, CTLA-4 is highly expressed in human pancreatic cancer cells." (PMID 33226370, 2020). "However, based on the early clinical trials, checkpoint inhibitors, such as anti-CTLA-4, anti-PD-1 or anti-PD-L1, are ineffective when used as monotherapy in the treatment of pancreatic cancer." (PMID 30987642, 2019). "Similarly, a patient exhibited regression of several pancreatic cancer metastases following administration of Ipilimumab (anti-CTLA4 mAbs)." (PMID 31024520, 2019). "However, there has been limited success in the use of checkpoint blockade immunotherapies such as PD1/CTLA4 antibodies or vaccines in the treatment of pancreatic cancer." (PMID 30809507, 2019). "Pan02 murine pancreatic cancer was resistant to both PD-L1 and CTLA4 antibodies." (PMID 29954062, 2018). "However, due to pancreatic cancer's unique characteristics, the treatment of single immune checkpoint inhibitor, anti-CTLA-4, anti-PD-1, or anti-PD-L1, has shown minimal clinical benefits in the treatment of advanced PDAC." (PMID 29707526, 2018). "Specifically, invasive Tregs in pancreatic cancer can bind to CD80/CD86 on the surface of dendritic cells via surface CTLA-4 to inhibit the function of dendritic cells in tissues, which, in turn, affects the function of cytotoxic CD8+ T cells to suppress immune responses in pancreatic cancer." (PMID 30477520, 2018). "Our present study revealed that tumors of mice receiving CIRT+HCQ‐treated pancreatic cancer cells were sensitive to anti‐CTLA4 mAb, whereas those receiving untreated control cells were resistant to it, indicating that CIRT might render cancer cells sensitive to Treg blockade." (PMID 40230051, 2025). "Similarly, a model established using m5C-related genes can also evaluate prognosis and immune therapy efficacy, with liver and pancreatic cancers with lower m5C scores being more sensitive to anti-CTLA-4 therapy, and pancreatic cancer also being sensitive to anti-PD-1 therapy." (PMID 39372415, 2024). "Therefore, combined treatment of personalized neoantigen-based peptide vaccines with anti-CTLA-4 antibody could potentially be a promising treatment modality for pancreatic cancer patients." (PMID 34484187, 2021). "Foxp3 and CTLA-4 mRNA expression are higher in Tregs from the peripheral blood of patients with progressed and advanced pancreatic cancer, and there should further be a positive correlation between the IL-10 or TGFβ levels and the progression of pancreatic cancer." (PMID 30060755, 2018). "Therefore, the immune therapy of pancreatic cancer with monoclonal antibody against CTLA4 (i.e., Ipilimumab) could be a new option for ameliorating a combination therapy." (PMID 24608924, 2014). "In a mouse pancreatic cancer model, inhibition of IL‐17‐stimulated NETosis has shown potent anti‐cancer effects and enhances sensitivity to ICIs (PD1, CTLA4)." (PMID 41503514, 2026). "Of greater significance, we noted that in several pancreatic cancer immunotherapy cohorts, patients with high GGCT expression demonstrated poorer response to Anti-PD-L1/CTLA-4 treatment and worse overall survival." (PMID 38914714, 2024). "This synergy has been reported in mouse pancreatic cancer in vivo models, where chloroquine enhanced MHC-class-I expression and antitumor T-cell response under dual anti-PD-1/CTLA4 immunotherapy." (PMID 39409895, 2024). "Several immune checkpoints, including TNFSF4, ICOS, CTLA4, and PDCD1, have been identified as playing crucial roles in the progression of pancreatic cancer." (PMID 37753069, 2023).
pancreatic cancer (continued). "Checkpoint inhibitor immunotherapy, consisting of anti-CTLA4 and anti-PD1, is effective in the treatment of a variety of cancers, and the feasibility of using immunotherapy to treat pancreatic cancer will receive increasing attention and research." (PMID 38097783, 2023). "Although pancreatic cancer is similarly resistant to ICB, combined anti-CTLA4 and anti-DKK3 antibodies showed synergistic antitumor responses in a pancreatic cancer model." (PMID 37847565, 2023). "A study in the Pan02 model of mouse pancreatic cancer revealed that the combination of agnostic anti-OX40 and inhibitory anti-CTLA4 led to transient decrease in ARG1 expression in TAMs, giving a therapeutic window for gemcitabine." (PMID 37251409, 2023). "A combination of CTLA-4 inhibitor, Ipilimumab, and cancer vaccine, GVAX has also been tested in previously treated advanced pancreatic cancer." (PMID 38107772, 2021). "For example, gemcitabine/abraxane instead of FOLFIRINOX in advanced pancreatic cancer, or de-escalation of doxorubicin/ifosfamide to doxorubicin in soft-tissue sarcoma, or early de-escalation of inductive immuno-oncological combination (CTLA-4/PD-1) to PD-1 monotherapy could be considered." (PMID 33759009, 2021). "Selection of currently ongoing clinical trials evaluating CTLA4 or/and PD1/PD-L1 checkpoint blockade in combination with untargeted and targeted options including other immunotherapeutic approaches for pancreatic cancer as indicated." (PMID 30158932, 2018). "Selection of currently ongoing clinical trials evaluating CTLA4 or/and PD1/PD-L1 checkpoint blockade in combination with targeted therapy approaches for pancreatic cancer as indicated." (PMID 30158932, 2018). "A reduced expression of CTLA4 among splenic MDSCs was observed in PDAC patients and was demonstrated to be consequent to the direct exposure of myeloid cell to pancreatic cancer derived products and in particular to the S100A8/A9 complex." (PMID 23359812, 2013). "Pancreatic cancer cell conditioned media effects on PDL1 and CTLA4 in immature myeloid cell subsets." (PMID 23359812, 2013). "It’s worth noting that comparable results have been observed in models of breast and pancreatic cancer, where the combination of CD73 targeting with RT, further augmented with CTLA-4 and PD-1 immune checkpoint inhibitors, respectively, demonstrated enhanced antitumor activity." (PMID 39285178, 2024). "The study demonstrated that the blockade of PD-1 alone, or in combination with CTLA-4, did not result in any improvement in efficacy in pancreatic cancer." (PMID 37366887, 2023). "Ipilimumab, a CTLA-4 inhibitor, alone and in combination with gemcitabine or Nivolumab (PD-1 inhibitor) and has been tested in unresectable/locally advanced/ metastatic stage III or IV pancreatic cancer." (PMID 38107772, 2021). "Immunotherapy with antibodies targeting PD-1, PD-L1, CTLA-4 has not shown clinical activity in unselected pancreatic cancer, emphasizing the need for combination immunotherapy approaches or other therapeutic strategies." (PMID 30319627, 2018). "Despite the emergence of immune checkpoint blockade as a promising new treatment for cancers, a majority of cancer patients, including pancreatic cancer patients, do not benefit from monotherapy with PD-L1 or CTLA-4 blockade." (PMID 27343548, 2016). "Despite the promising efficacy of immune checkpoint blockade in some types of cancer, monotherapy with PD-1 and CTLA-4 blockade has not proved effective in many cancer types, including pancreatic cancer." (PMID 27343548, 2016). "Further endpoints were to assess whether pancreatic cancer cells are able to expand MDSCs in vitro and to evaluate the role of the inhibitory co-stimulatory molecules PDL1 and CTLA4 searching also for any potential effect of the S100A8 and S100A9 molecules." (PMID 23359812, 2013).
pancreatic cancer (continued). "In an experimental study in experimental pancreatic cancer on mice, the combination of anti-PD-1 with anti-CTLA-4 resulted in higher T cell infiltration and tumor response, while blocking CSF-1/CSF-1R resulted in elevated PD-1/PD-L1 expression on TAMs and increased CTLA-4 expression on CD8+ T cells." (PMID 38541123, 2024). "Furthermore, blockage of CTLA-4/CD80 interaction is sufficient to induce CD4+ T cell infiltration into pancreatic tumours, demonstrating that the CTLA-4/CD80 axis regulates T cell infiltration in pancreatic cancer." (PMID 35892707, 2022). "Checkpoint inhibitors, against molecules such as PD-1, CTLA4, TIM-3, and LAG-3 have shown promise as single agents in a number of cancer types but unfortunately, none of these treatment as a single therapy has generated significant clinical benefit in pancreatic cancers." (PMID 30809507, 2019). "The reduced CTLA4 expression found among splenic IMCs of PDAC patients was demonstrated to characterize an immune suppressive phenotype and to be consequent to the direct exposure of myeloid cells to pancreatic cancer derived products, S100A8/A9 complex in particular." (PMID 23359812, 2013). "Interestingly, unresectable, non-metastatic pancreatic cancer is also being investigated in a phase Ib clinical study (NCT02868632) to evaluate the efficacy of RT plus either anti-CTLA-4 mAb alone, anti-PD-L1 mAb alone, or the combination of both immune checkpoint inhibitors." (PMID 30987642, 2019). "In pancreatic cancer, not responding to ICB therapy, a combination of anti-PD1 or anti-CTLA-4 checkpoint immunotherapy with PLX3397 improved anti-tumor immunity and led to the regression of established primary pancreatic tumors." (PMID 31878087, 2019). "One study found that, in patients with pancreatic cancer, there was a lack of correlation between T‐cell TIM3 immunohistochemistry (IHC) expression and patient prognosis; however, patients in this study did not receive anti‐PD‐1/PD‐L1, anti‐CTLA‐4, nor anti‐TIM‐3 treatments." (PMID 38132831, 2023).
type 1 diabetes (108 papers, 2002 to 2026). "Specific HLA haplotypes and polymorphisms in the CTLA-4 and PD-1 genes have been associated with an increased risk of autoimmune β cell destruction and the onset of type 1 diabetes mellitus (T1DM) following ICI therapy." (PMID 40559409, 2025). "Type 1 diabetes-associated CTLA4 risk allele decreased sCTLA-4 isoform relative to the full-length isoform, which impairs the suppressive activity of Treg cells." (PMID 40007754, 2025). "Single nucleotide polymorphisms (SNPs) in CTLA4 are strongly associated with autoimmune diseases such as Type 1 diabetes mellitus (T1D), Graves’ disease, and lupus erythematosus (SLE)." (PMID 37176151, 2023). "Another study involving a non-obese diabetic mice model showed that using ASOs to modify CTLA-4 isoform ratios can significantly change the pathogenic outcomes of type 1 diabetes in mice." (PMID 37895245, 2023). "Cytotoxic T-lymphocyte associated protein 4 (CTLA4) is involved in T-cell immune responses, and thus, it regulates the pathogenesis of insulin resistance and insulin-dependent diabetes mellitus." (PMID 34516309, 2021). "Mutation or polymorphism of the CTLA-4 gene leads to an uncontrolled proliferation response, which can be the cause of autoimmune diseases including type 1 diabetes." (PMID 34836227, 2021). "Genetics have a crucial role in the susceptibility of diabetes type 1; the most common genes related to type 1 diabetes are CTLA-4, PTPN22, STAT4, STAT3, and IFIH1." (PMID 34342790, 2021). "Epigenetic analysis in case of type 1 diabetes revealed that high level of methylation H3K9me in CTLA4 (T1D susceptibility gene) correlates with T cell activation." (PMID 32899152, 2020). "CTLA-4 gene polymorphisms correlate with autoimmune diseases such as systemic lupus erythematosus, type 1 diabetes mellitus and Graves’ disease." (PMID 27118383, 2016). "A possible link between HLA polymorphisms and expression of CTLA4 has also been suggested in human type 1 diabetes, although further studies are required to confirm the association between HLA and CTLA4." (PMID 26401336, 2015). "In the past decade, a number of case–control studies have been carried out to investigate the relationship between the CTLA4 gene polymorphisms and type 1 diabetes (T1D)." (PMID 24465825, 2014). "Out of the 69 regions reported in the GWAS catalog for type 1 diabetes, eight overlap with the regions reported in this study and out of those eight, CTLA4/ICOS also overlap with the previously reported CD associations." (PMID 23936387, 2013). "Ever since the relationship between CTLA-4 polymorphisms and G-B disease and type 1 diabetes in southern European countries was demonstrated for the first time, numerous studies have been conducted to link a given polymorphism with a specific disease." (PMID 23072316, 2012). "For example, splice variants of the T cell inhibitory receptor CTLA-4 are associated with susceptibility to type 1 diabetes and autoimmune thyroid disease." (PMID 22768209, 2012). "Association of type-1 diabetes, Graves’ disease and CD with a point mutation in exon 1 of CTLA-4 (i.e. position 49A/G) leading to a Thr/Ala substitution in the leader peptide has been described in several different populations." (PMID 23049754, 2012). "On the other hand, SNPs in CTLA-4 are associated with disease risk in Grave's disease, autoimmune hypothyroidism, and type I diabetes." (PMID 21403914, 2011). "SNPs in CTLA-4 are associated with disease risk in Grave's disease, autoimmune hypothyroidism, and type I diabetes." (PMID 21403914, 2011). "A recent publication has shown evidence for association of another SNP within the CTLA4 with type 1 diabetes, the rs1427676." (PMID 20537165, 2010). "The CTLA4 gene is associated with other immunopathologic diseases (type 1 diabetes, Graves' disease, Addison's disease, celiac disease, systemic lupus erythematosus, rheumatoid arthritis, vitiligo)." (PMID 20537165, 2010).